SPATA31G1 (SPATA31 subfamily G member 1)
Description:
Dispensable for normal development and fertility.
Synonyms: C9orf131; MGC41945
Tractability: PROTAC: ubiquitination databases record sites on it.
Gene: Protein-coding gene on chromosome 9 (35,041,095 to 35,045,986, forward strand). Ensembl gene ENSG00000174038.
Subcellular location (Human Protein Atlas): Mitochondria
Genetic constraint (gnomAD): Loss-of-function variants: 11 observed, 11.43 expected, observed/expected ratio (o/e) 0.96, 90% interval 0.6 to 1.58. The upper end of that interval is the gene's LOEUF score, 1.58, which puts it in group 6 of 6, group 1 being the genes least tolerant of losing a copy. Missense variants: 1,368 observed, 1,365.2 expected, observed/expected ratio (o/e) 1, 90% interval 0.96 to 1.05. Synonymous variants: 490 observed, 530.91 expected, observed/expected ratio (o/e) 0.92, 90% interval 0.86 to 1.
Homologues: Orthologues: chimpanzee SPATA31G1 (97% identical), macaque SPATA31G1 (90% identical), dog C11H9orf131 (59% identical), rat Spata31g1 (51% identical), pig SPATA31G1 (51% identical), mouse Spata31g1 (48% identical).
Diseases named in the same sentence as SPATA31G1 in open-access papers:
SPATA31G1 is named in the same sentence as 1 disease in open-access papers, as found by Europe PMC text mining. Sharing a sentence is not in itself a finding about the gene and the disease.
SPATA31G1 shares sentences with these, for which no sentence is quoted: male infertility (1 paper).